IRF8 (interferon regulatory factor 8)
Description:
Transcription factor that specifically binds to the upstream regulatory region of type I interferon (IFN) and IFN-inducible MHC class I genes (the interferon consensus sequence (ICS)). Can both act as a transcriptional activator or repressor (By similarity). Plays a negative regulatory role in cells of the immune system (By similarity). Involved in CD8(+) dendritic cell differentiation by forming a complex with the BATF-JUNB heterodimer in immune cells, leading to recognition of AICE sequence (5'-TGAnTCA/GAAA-3'), an immune-specific regulatory element, followed by cooperative binding of BATF and IRF8 and activation of genes (By similarity). Required for the development of plasmacytoid dendritic cells (pDCs), which produce most of the type I IFN in response to viral infection (By similarity). Positively regulates macroautophagy in dendritic cells. Acts as a transcriptional repressor of osteoclast differentiation factors such as NFATC1 and EEIG1 (By similarity).
Synonyms: IRF-8; H-ICSBP; ICSBP; ICSBP1; IMD32A; IMD32B
Tractability: PROTAC: UniProt records ubiquitination sites on it; ubiquitination databases record sites on it; its protein half-life has been measured.
Gene: Protein-coding gene on chromosome 16 (85,899,116 to 85,922,606, forward strand). Ensembl gene ENSG00000140968.
Subcellular location: Nucleus; Cytoplasm
Subcellular location (Human Protein Atlas): Nucleoplasm
Pathways (Reactome):
Immune System: Interferon alpha/beta signaling; Interferon gamma signaling
Gene Ontology:
Molecular function: DNA-binding transcription repressor activity, RNA polymerase II-specific; protein binding; RNA polymerase II cis-regulatory region sequence-specific DNA binding; sequence-specific double-stranded DNA binding; DNA-binding transcription factor activity, RNA polymerase II-specific; DNA binding; DNA-binding transcription factor activity; RNA polymerase II transcription regulatory region sequence-specific DNA binding; transcription cis-regulatory region binding
Biological process: cellular response to type II interferon; negative regulation of transcription by RNA polymerase II; positive regulation of transcription by RNA polymerase II; dendritic cell differentiation; immune response; immune system process; plasmacytoid dendritic cell differentiation; regulation of transcription by RNA polymerase II; regulation of type I interferon production; defense response to other organism; follicular B cell differentiation; germinal center B cell differentiation; positive regulation of apoptotic process; regulation of DNA-templated transcription
Cellular component: cytoplasm; nucleoplasm; nucleus; chromatin; cytosol
Genetic constraint (gnomAD): Loss-of-function variants: 14 observed, 47.33 expected, observed/expected ratio (o/e) 0.3, 90% interval 0.19 to 0.46. The synonymous counts are far from expectation, so gnomAD's model fits this gene poorly and the ratio says little. Missense variants: 488 observed, 574.16 expected, observed/expected ratio (o/e) 0.85, 90% interval 0.79 to 0.92. Synonymous variants: 276 observed, 224.42 expected, observed/expected ratio (o/e) 1.23, 90% interval 1.11 to 1.36.
Homologues: Orthologues: chimpanzee IRF8 (99% identical), macaque IRF8 (99% identical), dog IRF8 (92% identical), mouse Irf8 (89% identical), pig IRF8 (88% identical), rat Irf8 (88% identical), rabbit IRF8 (81% identical), tropical clawed frog irf8 (64% identical), zebrafish irf8 (53% identical). Paralogues in human: IRF4 (44% identical), IRF5 (30% identical), IRF9 (29% identical), IRF6 (28% identical), IRF3 (23% identical), IRF7 (22% identical), IRF2 (18% identical), IRF1 (18% identical).
Diseases named in the same sentence as IRF8 in open-access papers:
IRF8 is named in the same sentence as 247 diseases in open-access papers, as found by Europe PMC text mining. Sharing a sentence is not in itself a finding about the gene and the disease. The quoted sentences say what the papers report.
lupus (29 papers, 2011 to 2026). "By dissecting an autoimmune disease genetic locus, the authors define an immune cell-type-specific enhancer and the molecular mechanisms underlying the dysregulation of IRF8 expression by lupus risk variants." (PMID 35388006, 2022). "For example, IRF8 deficiency affects plasmacytoid dendritic cell development and reduces the autoimmunity in lupus-prone NZB mice." (PMID 35388006, 2022). "Early studies have shown that congenic lupus-predisposed mice lack pDCs because of IRF8 deficiency or SLC15A4 mutation." (PMID 29085361, 2017). "A recent study of serologic and cytokine profiles in patients with systemic lupus erythematosus also demonstrated an association between an IRF8 variant (rs17445836) and decreased levels of IFIT1." (PMID 25880423, 2015). "The genetic polymorphisms (rs2280381, rs11644034) in IRF8 (interferon regulatory factor 8) have been confirmed to confer susceptibility to lupus in European populations." (PMID 25890262, 2015). "Strong and independently replicated associations have been detected between polymorphic variants within or near IRF8 gene for systemic lupus erythematosus, ulcerative colitis, Crohn's disease, and multiple sclerosis (MS)." (PMID 23853600, 2013). "The lupus variant influences IRF8 gene expression, since LCLs from three HapMap cohorts, showed a significant increase in IRF8 transcript levels in homozygotes for the risk allele (TT) compared to homozygotes for the non-risk allele (CC) (P = 0.045)." (PMID 22046141, 2011). "IRF7 itself has been identified as a risk factor for human systemic lupus erythematosus and has been shown to be co-regulated along with IRF8 in MS." (PMID 22196084, 2011). "Moreover, this genetic variation, rs17445836G, was notably associated with increased levels of IRF8 expression in B cells among individuals diagnosed with Systemic Lupus Erythematosus (SLE)." (PMID 39810445, 2025). "We identified two transcription factors (STAT1 and LTF) that were positively correlated with T-cell subset infiltration in the lupus tubulointerstitium, and three transcription factors (IRF8, RORC and IKZF2) that were positively associated with T-cell subset infiltration in the glomeruli." (PMID 36829595, 2023). "Our work illustrates an integrative strategy to define functional genetic variants that regulate the expression of critical genes in autoimmune diseases and decipher the mechanisms underlying the dysregulation of IRF8 expression mediated by lupus risk variants." (PMID 35388006, 2022). "Coronary heart disease in systemic lupus erythematosus (SLE) is associated with a polymorphism of the IRF8 gene." (PMID 27166190, 2016). "Here, we present evidence for the Irf8 gene as a lupus protective factor in conditions of haploinsufficiency or mosaicism." (PMID 41668764, 2026). "While IRF1, IRF3, IRF5, and IRF8 predominantly exacerbate AS, context-dependent roles (e.g., IRF5 in lupus-associated AS) highlight their therapeutic complexity." (PMID 40980176, 2025). "Validation through qRT-PCR and WB confirmed that the IRF8 gene and its protein exhibited elevated expression levels in the kidneys of lupus mice compared to control groups." (PMID 39717551, 2024). "This study, primarily focused on validating the differential expression of the IRF8 gene in lupus mouse models, encounters several limitations." (PMID 39717551, 2024). "To validate the expression levels of the IRF8 gene in the kidneys of lupus mice models, we used quantitative real-time PCR (qRT-PCR) and Western blotting (WB)." (PMID 39717551, 2024). "For example, a risk variant for systemic lupus erythematosus (SLE), rs2280381, is found in an area of the distal enhancer that regulated IRF8 expression by spatially interacting with the IRF8 promoter and influencing methylation levels." (PMID 37346038, 2023).
lupus (continued). "Peripheral blood mononuclear cells from systemic lupus erythematosus patients are characterized by elevated phosphorylation of IRF8 at the same Serine residue we find to be important in STING activation, and in these cells STING is hyper-active." (PMID 35973990, 2022). "Of note, the lupus-susceptibility risk loci PTPRC, NCF1 and ITGAM genes, as well as the IRF8,33–35 emerged as hub network genes, suggesting a pathogenic role during evolution from preclinical to clinical LN." (PMID 35906002, 2022). "The findings revealed a novel mechanism linking IRF-8/miR-451a to M-MDSC differentiation via the AMPK/mTOR signal pathway during lupus development." (PMID 34282122, 2021). "In terms of mechanism, whole-genome transcriptome profiling was performed by RNA sequencing, revealing that the expression of the transcription factor IRF-8 was higher in M-MDSCs isolated from pristane-induced lupus mice, compared with control mice." (PMID 34282122, 2021). "The expression of IRF-8 in M-MDSCs was found to be higher than that in G-MDSCs in both lupus BM-derived MDSCs and spleen-derived MDSCs." (PMID 34282122, 2021). "Meanwhile, the expression of IRF-8 in G-MDSCs from mice with lupus was lower than that in control mice." (PMID 34282122, 2021). "This study aimed to assess the association between 14 single nucleotide polymorphisms (SNPs) in six genes (IRF8, TMEM39A, IKZF3, ORMDL3, GSDMB, and ZPBP2) and systemic lupus erythematosus (SLE) in a Chinese Han population sample." (PMID 28427360, 2017). "Despite these intriguing observations, pDCs’ influence on lupus pathogenesis remains uncertain because both Irf8 and Slc15a4 affect the development or function of other immune cell types." (PMID 26528288, 2015). "In this process, we identified pathways enriched within each signature and found that hub genes correspond to lupus susceptibility risk loci (such as the PTPRC, ITGAM, NCF1 and IRF8 genes), reinforcing their pathogenic role in LN and the progression from preclinical to clinical kidney disease." (PMID 35906002, 2022). "While further elucidating the molecular mechanisms involved in the differentiation of MDSCs in lupus, the expression of the transcription factor IRF-8 was found to be higher in M-MDSCs isolated from mice with pristane-induced lupus compared with control mice, with low expression in G-MDSCs." (PMID 34282122, 2021). "We found that persistent LCMV infection (0.89 ± 0.23 × 105 PFU/mL at 3 mo of age) failed to precipitate lupus manifestations in pDC-deficient Irf8−/−NZB mice." (PMID 30199535, 2018). "SLC15A4-, MyD88-, IRF8-, or IRF5-deficient lupus-prone mice have shown ameliorated lupus symptoms with reduced IFNα protein level in the serum, decreased IFNα transcript level in pDC, downregulation of type I IFN inducible genes, and suppressed activation of both T cells and B cells." (PMID 27034965, 2016). "By comparing allele frequencies between systemic lupus erythematosus patients with and without coronary heart disease, single-nucleotide polymorphisms located in the IRF8 gene were identified to be associated with the presence of carotid plaques and increased intima-media thickness." (PMID 39840103, 2024). "We also detected the expression of p-AMPK, p-mTOR and IRF-8 in kidney in pristane-induced lupus mice and found that IRF-8 and mTOR were highly expressed in the kidney tissues of SLE mice, and INK128 and metformin could significantly inhibit the expression of IRF-8 and the phosphorylation of mTOR." (PMID 34282122, 2021). "These 31 loops involved 22 lupus haplotypes, with ETV3-FCRL5, BLK, and IRF8 haplotypes containing more than one significantly differential loop." (PMID 40437445, 2025). "IRF1, IRF8, and STAT1 are important in human inflammatory diseases including systemic sclerosis, systemic lupus erythematosus, and inflammatory bowel disease." (PMID 36091020, 2022).
lupus (continued). "For example, in the lupus microenvironment, factors such as IFN-α and TLR-7 agonists could shift the MDSC differentiation towards M-MDSCs along with an increased level of IRF-8 while decreasing G-MDSCs." (PMID 40725182, 2025). "Next, to investigate whether IRF-8 was essential for the differentiation of MDSC subtypes, M-MDSCs and G-MDSCs were separately purified from spleens in mice with lupus and control mice using a MDSC isolation kit." (PMID 34282122, 2021). "To address this issue, we assessed lupus progression in WT and Irf8−/−NZB mice neonatally infected or not with LCMV." (PMID 30199535, 2018). "IRF8 and SLC15A4 may therefore be important targets for therapeutic intervention in lupus." (PMID 29085361, 2017).
leukemia (23 papers, 2011 to 2024). A malignant (clonal) hematologic disorder, involving hematopoietic stem cells and characterized by the presence of primitive or atypical myeloid or lymphoid cells in the bone marrow and the blood. "We hypothesize that cooperation of such leukemia-associated mutations with an age-associated decrease in Irf8, and thereby Nore1a, may define such mechanisms." (PMID 37247756, 2023). "In addition to mice mutated in Pax5 or Ikzf1, Irf4/Irf8−/−, and Irf4/Spi1−/− mice have been shown to develop leukemia early in life at a high incidence." (PMID 35459909, 2022). "Irf8 functions as a leukemia suppressor for chronic myeloid leukemia, and young Irf8−/− mice have neutrophilia with progression to acute myeloid leukemia (AML) with aging." (PMID 37247756, 2023). "Identifying Nore1a downstream from Irf8 defines a pathway involved in leukemia suppression and the innate immune response and suggests a novel molecular mechanism contributing to age-related clonal myeloid disorders." (PMID 37247756, 2023). "NUP98 mutations in leukemias are associated with mutations affecting apoptosis, such as BCR-ABL, NRAS, or KRAS and ICSBP (also known as IRF8)." (PMID 35107131, 2022). "We independently confirmed the selective dependency of KMT2Ar leukemia on IRF8 and MEF2D by measuring cell viability after CRISPR–Cas9 TF knockout in a panel of six cell lines." (PMID 35301220, 2022). "The expression level of IRF-8 influences the processes of various diseases ranging from infection to leukemia profoundly, and indicates that IRF-8 plays a key role in development of myeloid cells." (PMID 35211408, 2022). "The observation that KMT2A-rearranged leukemias depend on the IRF8/MEF2D axis for expression of common leukemia oncogenes raises the question of how expression of these oncogenes is maintained in non-KMT2Ar contexts." (PMID 35301220, 2022). "Most studies that describe a tumor-suppressor role of IRF8 in leukemia refer to CML or the AML M3 subclass APL." (PMID 33673123, 2021). "We identified involvement of Fap1 and Calpain in apoptosis resistance in CML while investigating mechanisms of leukemia suppression by the Interferon Consensus Sequence Binding Protein (Icsbp, also referred to as Interferon Regulatory Factor 8; Irf8)." (PMID 28881589, 2017). "Nevertheless, the reduced leukemia burden after Irf8 induction was much less due to an inhibited cell cycle or a prompted apoptosis induction." (PMID 28492552, 2017). "Eight genes (BAALC, CD14, CD34, CD74, DNTT, HLA-DRA, IRF8, and MN1) were all associated with “leukemia” (P = 1.15 × 10−4), “acute myeloid leukemia” (P = 9.37 × 10−3), and “proliferation of myeloid cells” (P = 0.044)." (PMID 26517675, 2015). "We had previously shown that interferon regulatory factor (IRF)-8, originally discovered as a leukemia suppressor gene by regulating apoptosis, also regulates Fas-mediated killing in non-hematologic tumor models." (PMID 23028998, 2012). "Irf8 is also required to terminate emergency granulopoiesis during the innate immune response, suggesting this may be the physiologic counterpart to leukemia suppression by this transcription factor." (PMID 37247756, 2023). "We next determined the effect of SNDX-5613 on in vivo leukemia-initiating potential of primary PD AML cells harboring MLL-AF9 plus FLT-3 N676T, as well as mutations in KMT2C, KMT2D, NOTCH2, IRF8, ARID1A, VPS13A, and ABCA7, which were determined by whole-exome sequencing." (PMID 35017466, 2022). "Importantly, rather than regulating a KMT2Ar-specific transcriptional program, the IRF8/MEF2D module enforces expression of ubiquitous leukemia oncogenes." (PMID 35301220, 2022). "Interestingly, previous studies proposed that IRF8 acts as a tumor suppressor in some leukemia types, while our analyses strongly support an oncogenic function of IRF8 in human AML." (PMID 33673123, 2021). "Therefore, the question arises how these seemingly contradictory roles of IRF8 in distinct leukemia types can be explained." (PMID 33673123, 2021).